EIF6 (eukaryotic translation initiation factor 6)
Diseases named in the same sentence as EIF6 in open-access papers (continued):
Sharing a sentence is not in itself a finding about the gene and the disease.
biliary tract cancer (1 paper, 2019). "Kaplan–Meier curves were generated to assess a potential association of EIF6 expression with overall survival in biliary tract cancer (BTC) patients." (PMID 31586263, 2019). "High levels of eIF6 correlated with shorter overall survival in biliary tract cancer (BTC) patients (n = 28)." (PMID 31586263, 2019). "Finally, we assessed the therapeutic potential of targeting eIF6 by performing siRNA-mediated knockdown experiments in two biliary tract cancer (BTC) cell lines (TFK-1, Mz-ChA-2)." (PMID 31586263, 2019).
colorectal adenoma (1 paper, 2021). An adenoma that arises from the colon or rectum. "Some scholars have found significantly enriched eIF6 expression and PI3K/AKT/mTOR signals in colorectal adenomas." (PMID 34922580, 2021).
endometrial cancer (1 paper, 2019). Primary or metastatic malignant neoplasm involving the endometrium (mucous membrane that lines the endometrial cavity). "We further investigated the expression patterns of peIF2α, eIF2α, eIF3c, eIF3h, eIF4e, eIF4g, eIF5 and eIF6 in endometrial cancer compared to non-neoplastic patient samples using immunoblot analysis." (PMID 31817792, 2019).
esophagus adenocarcinoma (1 paper, 2022). "High eIF6 expression was significantly correlated with shorter overall survival of patients with esophagus adenocarcinoma (p = 0.038), but not in squamous cell carcinoma of the esophagus (p = 0.078)." (PMID 35794622, 2022).
fibrosis (1 paper, 2016). the formation of excess fibrous connective tissue in an organ or tissue in a reparative or reactive process. "We were therefore motivated to ask whether eIF6 is involved in mechanical force-mediated fibrosis, and implemented an in vitro external mechanical stretch model using the Flexcell tension system." (PMID 27824055, 2016).
gallbladder tumor (1 paper, 2019). "Moreover, the IHC staining of GBC for eIF6 revealed its overexpression in the cytoplasm of gallbladder tumor cells, whereas staining intensity and density were less in non-neoplastic gallbladder tissue." (PMID 31586263, 2019).
glioblastoma (1 paper, 2024). The most malignant astrocytic tumor (WHO grade IV). "The overactivation of eIF6 has been confirmed to be associated with tumor proliferation and invasion through the AKT and mTOR pathways in oral squamous cell carcinoma, glioblastoma, and colorectal cancer." (PMID 38238581, 2024).
skin melanoma (1 paper, 2022). "However, the role of eIF6 in the skin cutaneous melanoma progression and its potential as a prognostic marker is still unexplored." (PMID 35707354, 2022).
tumor (35 papers, 2012 to 2025). "circ-EIF6 (hsa_circ_0060055) encodes a 224-aa peptide (EIF6-224aa) in a study to determine the role of the Wnt/ β-catenin pathway in tumor metastasis." (PMID 38877495, 2024). "Higher eIF6 expression levels associated positively with tumor progression, suggesting that eIF6 can serve as a prognostic biomarker for patients with LUAD." (PMID 36435920, 2023). "Our data demonstrated that compared with the normal esophageal tissues, eIF6 expression was upregulated in ESCA tumor tissues and showed a high diagnostic value with an area under curve of 0.825 for predicting ESCA." (PMID 35794622, 2022). "Nowadays, the tumor-promoting pathways associated with eIF6 have been found in various types of cancer cells." (PMID 35707354, 2022). "Cells overexpressing eIF6 grew faster (higher tumor weight and volume) than the cells expressing eIF6 encoding vectors or control vectors." (PMID 34922580, 2021). "High cytoplasmic eIF6 staining was significantly associated with advanced tumor size, lymph node metastasis, and clinical stage." (PMID 34922580, 2021). "In order to determine the function of eIF6 in tumor progression, we performed gain-of-function or loss-of-function assays in HN4 and HN6 OSCC cell lines." (PMID 34922580, 2021). "By using calretinin as a diagnostic marker for MPM, we confirmed that eIF6 overexpression was limited to tumor cells." (PMID 26462016, 2015). "We show that a number of membrane-associated proteins indeed vary in abundance upon eIF6 over-expression, and that the up-regulated proteins can be located within a functional network controlling cell motility and tumor metastasis." (PMID 25886394, 2015). "In human cancers, eIF6 is highly expressed in colorectal carcinomas, and its overexpression is associated with tumor stage." (PMID 26462016, 2015). "Over-expression of eIF6 is observed in many natural tumours, and causes developmental and differentiation defects in certain animal models." (PMID 22348144, 2012). "Here we show that the transcription of the gene encoding eIF6 is modulated by the receptor Notch-1, a protein involved in embryonic development and cell differentiation, as well as in many neoplasms." (PMID 22348144, 2012). "Circ-EIF6 is capable of encoding EIF6-224aa in enhancing tumor progression." (PMID 38334836, 2024). "Moreover, the Bulk RNA gene analysis revealed a significant inverse association between eIF6 and the tumor-infiltrating immune cells (macrophages, T cells, or Th1 cells) and immunomodulators in the ESCA microenvironment." (PMID 35794622, 2022). "We also asked whether the genes regulated by eIF6 actually belong to the subset of genes associated with tumor progression in human HCC." (PMID 34385447, 2021). "Based on the analysis of clinicopathological parameters, we also found that high levels of eIF6 had a positive correlation with tumor progression, and eIF6 may serve as a potential diagnostic and prognostic biomarker for HCC patients." (PMID 34016142, 2021). "In addition, data from the subcutaneous xenograft model in vivo also suggested that eIF6 deficiency could significantly delay tumor growth and improve the prognosis of mice." (PMID 36435920, 2023). "In addition, tumor eIF6 was significantly associated with 18F-FDG PET/CT parameters: maximal and mean standardized uptake values (SUVmax and SUVmean) and total lesion glycolysis (TLG) (rho = 0.458, 0.460, and 0.300, respectively, p < 0.01) as well as GLUT1 expression (rho = 0.453, p < 0.001)." (PMID 35794622, 2022). "Although the KD of circ-EIF6 alleviated tumor cell progression of TNBC, the study showed that EIF6-224aa activates the Wnt/beta-catenin pathway via interaction with MYH9 protein." (PMID 41208886, 2025).
tumor (continued). "Notable candidate genes included ANKH (12 associated SNPs), EIF6 (11 SNPs), and SLC4A7, DLG2, and FBXL7, which are widely implicated in cellular inflammation, immune response, and tumor development." (PMID 40427243, 2025). "The expression matrix from the TCGA-LUAD cohort was first downloaded and found that eIF6 expression was significantly higher in the tumor samples compared with that in the normal tissues according to the differential analysis." (PMID 36435920, 2023). "Higher eIF6 expression can promote tumor progression in vitro and in vivo, including increasing cell proliferation and migration." (PMID 36435920, 2023). "Future studies will assess the effect of targeting the eIF6–60S interaction interface on tumor progression in vivo." (PMID 36651285, 2023). "Since previous studies have already reported the association between eIF6 and cell cycle progression, the potential relationship between eIF6 expression and the tumor self-renewal features was next focused upon." (PMID 36435920, 2023). "Since it has been reported that eIF6 is essential for immune system homeostasis in both mice and humans, we also investigated the tumor immunology of eIF6." (PMID 35707354, 2022). "We next sought to determine the threshold of PET parameters that would predict tumor eIF6 status in primary ESCA." (PMID 35794622, 2022). "Third, further in-depth clinical research should be conducted to clarify the functional role of eIF6 in the tumor immunosuppressive microenvironment." (PMID 35794622, 2022). "On the other hand, the bioinformatics analyses suggested that eIF6 is involved in metabolic pathways and tumor immune infiltration in ESCA." (PMID 35794622, 2022). "The poor survival rate of the eIF6 high expression group suggested that eIF6 profoundly impacted the tumor cells." (PMID 35707354, 2022). "Our IHC analysis revealed that tumor eIF6 expression was positively correlated with FDG PET parameters in ESCA tissues." (PMID 35794622, 2022). "The expression of tumor eIF6 and glucose transporter 1 (GLUT1) was examined using immunohistochemical tools in fifty-two ESCA patients undergoing routine 18F-FDG PET/CT before surgery." (PMID 35794622, 2022). "For instance, in the myc-induced lymphomas mice model, eIF6 impairment can significantly reduce the tumor growth and prolong the tumor-free survival time through an mTORC-independent mechanism." (PMID 35707354, 2022). "eIF6 translational activity is a central regulator of tumorigenesis and tumor growth because of its capability to upregulate fatty acid accumulation at the translational level." (PMID 35887068, 2022). "To explore the anti-tumor effect of eIF6 on human ESCA, we evaluated the eIF6 protein expression in four ESCA cell lines and a human epithelial cell line (HET1A)." (PMID 35794622, 2022). "Investigation in OC cell lines showed, that eIF6 expression was connected to motility and tumour metastasis." (PMID 35718769, 2022). "The subunits involved in the translational machinery of OC in tumour tissue or cell lines has been reported for eIF6, eIF5A, eIF5B, eEF1 and eIF2α." (PMID 35718769, 2022). "The results obtained in vivo suggest that a modest inhibition of eIF6 activity is sufficient to inhibit tumor growth." (PMID 35887068, 2022). "We then performed IHC analysis in fifty-two patients and showed that the tumor tissues had higher expression of eIF6 compared with normal epithelia tissues (p < 0.05)." (PMID 35794622, 2022). "In other words, patients with large tumor diameters or vascular invasion occurrences were frequently identified with eIF6 overexpression." (PMID 34016142, 2021).
tumor (continued). "Functional studies indicated that the deletion of eIF6 displayed tumor-suppressor activity in HCC cells." (PMID 34016142, 2021). "In normal oral mucosa, eIF6 was mostly confined to the nucleus with lower expression compared with tumor tissues." (PMID 34922580, 2021). "The data show that the expression of eIF6 was significantly correlated with tumor size (p<0.001) and vascular invasion (p<0.001)." (PMID 34016142, 2021). "We found that cytoplasmic eIF6 was abnormally highly expressed in OSCC tissues, and its expression was associated with tumor size and the clinical grade." (PMID 34922580, 2021). "In our previous study, we have discovered the oncogenic role of cytoplasmic eIF6 in tumor tissues by microarray analysis." (PMID 34922580, 2021). "The findings of this study provided a novel basis for understanding the potential role of eIF6 in promoting tumor growth and invasion, and exploited a promising strategy for improving diagnosis and prognosis of HCC." (PMID 34016142, 2021). "The background of our study was the discovery of translational control of lipid synthesis driven by eIF65,14, combined with the fact that eIF6 reduction impairs tumor progression." (PMID 34385447, 2021). "In the clinic, eIF6 is expected to become an essential criterion for diagnosing the tumor condition and judging the prognosis." (PMID 34922580, 2021). "Cells treated with the eIF6 knockdown (Sh) or control (NC) were injected into nude subcutaneous tissue, and the tumor size was measured 23days." (PMID 34016142, 2021). "Recently, emerging studies have also reported that eIF6 is an important factor in carcinogenesis and tumor progression." (PMID 34016142, 2021). "Morphometric analysis of the tumor mass revealed a higher percentage of small nodules in eIF6+/− mice, and a reduction of eIF6 protein levels." (PMID 34385447, 2021). "Taking into account all investigated eIFs, eIF6 appears to play the most important role in ITACs, followed by eIF2S1, with increased expression in tumour tissues compared with normal controls." (PMID 34830804, 2021). "We then conducted Transwell-Matrigel assays to study effect of eIF6 knockdown on tumor invasion in vitro." (PMID 34016142, 2021). "The eukaryotic translation initiation factors, namely, EIF1, EIF3E, EIF3H, EIF4G2, EIF5, and EIF6, were all upregulated in the brain metastasis-derived tumor cells." (PMID 33170151, 2020). "Overall, these data suggest that the modulation of the antiassociation activity of eIF6, which is known to be regulated by growth factor signaling pathways, can have a specific effect in tumor environments." (PMID 31936702, 2020). "eIF6 activity is heavily affected in tumor cells and its modulation has a potential value in both cancer and genetically inherited diseases." (PMID 31936702, 2020). "Strikingly, we found that eIF6 over-expression in turn up-regulates a set of proteins participating in a functional network known to control tumor cell motility." (PMID 25886394, 2015). "Our data fit a model in which eIF6-driven translation is a targetable feed-forward loop that induces insulin resistance and tumour growth." (PMID 26383020, 2015). "eIF6 is over-expressed in tumors and its decreased expression renders cells less prone to tumor growth." (PMID 25886394, 2015). "A previous work from our laboratory has disclosed that eIF6 transcription is under the control of the transmembrane receptor Notch-1, a protein involved in a wide variety of human neoplasms." (PMID 25886394, 2015). "The protective effects of eIF6 depletion on tumour growth and the specific action of eIF6 on insulin-stimulated translation suggest that eIF6 and 60S availability control the translation of specific mRNAs." (PMID 26383020, 2015).
tumor (continued). "We found that eIF6 transcription is under the control of the transmembrane receptor Notch-1, a protein involved in a wide variety of human neoplasms, as well as in embryonic development and cell differentiation." (PMID 22348144, 2012). "Research suggests that decreasing the EIF6 level in cytoplasm inhibited the development of tumor while increasing the level of nucleolus-stimulated tumor formation." (PMID 22734884, 2012). "Likewise, elevated eIF6 expression is identified in EC utilizing 18F-FDG PET/CT, with an SUVmax threshold of 18.2, resulting in a predictive accuracy of 0.755 for tumor eIF6 expression." (PMID 39399490, 2024). "In addition, the expression levels of eIF6 were observed to be higher in tumor samples compared with those in normal lung tissues via another GEO datasets, including GSE81809 (n = 199) and GSE68465 (n = 443)." (PMID 36435920, 2023). "Therefore, a subcutaneous xenograft tumor model was established, which found that eIF6 KO can suppress tumor growth in vivo to improve the OS time of mice, compared with the tumors derived from the parental cells." (PMID 36435920, 2023). "Subsequently, a subcutaneous xenograft model was established as previously reported, which found that eIF6 knockout could markedly delay tumor growth compared with that derived from the control cells, as indicated by the tumor volume and weight measurements." (PMID 36435920, 2023). "Eukaryotic initiation factors (eIFs) consisting of eIF4E, eIF2, eIF6 and so on are the main regulators in the initial stage of mRNA translation, whose abnormal expression has been confirmed to be involved in tumor progression, including proliferation, anti-apoptosis, and metastasis." (PMID 35737644, 2022). "Under these conditions, we found that each eIF6 shRNA inhibited the growth of the tumor spheroid." (PMID 35887068, 2022). "In conclusion, this study shows that eIF6 is highly expressed in ESCA tumor tissues and could predicted worse prognosis." (PMID 35794622, 2022). "Notably, inhibition of either eIF4E or eIF6 results in the reduction of oncogenesis and tumor growth." (PMID 35887068, 2022). "A SUVmax cutoff of 18.2 led to prediction of tumor eIF6 expression with an accuracy of 0.755." (PMID 35794622, 2022). "Our study suggested that eIF6 might serve as a potential prognostic biomarker associated with metabolic variability and immune gene signatures in ESCA tumor microenvironment." (PMID 35794622, 2022). "Moreover, a previous systematic review demonstrated that eIF6 promoted glycolytic flux and fatty acid synthesis and increased tumor viability." (PMID 35794622, 2022). "By contrary, eIF6 depletion attenuated tumor formation in vivo." (PMID 34922580, 2021). "In 25 tumor tissues, eIF6 was expressed in both nucleus and cytoplasm." (PMID 34922580, 2021). "Mechanistically, eIF6 promoted tumor progression by activating the AKT signaling pathway." (PMID 34922580, 2021). "eIF6 is the primary regulator of translation and tumor progression in vivo." (PMID 34922580, 2021). "Knockdown of eIF6 arrested tumor growth in a nude subcutaneous xenograft model." (PMID 34016142, 2021). "eIF6 is an accelerator of tumorigenesis and tumor progression." (PMID 34385447, 2021). "In addition, functional studies indicated that eIF6 was a potential driver of tumor biological processes in vitro and in vivo cancer models." (PMID 34016142, 2021). "In eIF6+/− heterozygous knockout mice, tumor-free survival was observed, suggesting that eIF6 might limit tumor progression." (PMID 31586263, 2019). "In summary eIF6 activity is required for a glycolytic switch that may account for its need for tumor growth in vivo." (PMID 26462016, 2015). "In general, eIF6 is rate limiting for tumor onset and progression." (PMID 26462016, 2015). "Data showed that 35/42 MPM patient datasets expressed higher levels of eIF6 mRNA in tumor samples." (PMID 26462016, 2015). "eIF6 phosphorylation of Ser235 has been reported in several tumor cells." (PMID 26462016, 2015).